CXCL12 (C-X-C motif chemokine ligand 12)
Diseases named in the same sentence as CXCL12 in open-access papers (continued):
Sharing a sentence is not in itself a finding about the gene and the disease.
tumor (continued). "We ran simulations of the tumor microenvironment (Setup 2) for 24 hours and included two circadian sources of CXCL12: CXCL12 in the blood and CXCL12 secreted by cells within the tissue." (PMID 29117251, 2017). "QRHX inhibited tumor cell-TAMs interactions via the suppression of cancer-related inflammation and probably blocking the response of macrophages to tumor signals, CXCL12/CXCR4/JAK2/STAT3 axis." (PMID 28630636, 2017). "Third, the magnitude and direction of CXCL12 gradients are dependent on the local composition of secreting and scavenging cells within the tumor." (PMID 29117251, 2017). "NOXXON Pharma target chemokine receptor CXCL12, with the aim of increasing the sensitivity of tumor cells to drugs and immune cells." (PMID 28620386, 2017). "In tumors, chemokines such as CCL2, CCL5, IL-8, and CXCL-12 also chemoattract TAMs to the tumor site." (PMID 28545495, 2017). "CAFs are present within BCC stroma and associated with increased expression of chemokines involved in tumour progression and immunosuppression (CXCL12, CCL17)." (PMID 28987144, 2017). "We found a high expression of CXCL12 in the peritumoural skin but low expression within BCC highlighting a role for CXCL12 primarily in the tumour microenvironment surrounding BCC." (PMID 28987144, 2017). "It has been shown to promote angiogenesis, invasion and metastasis by leading tumor cells to tissues that release CXCL12." (PMID 28038471, 2017). "Considering the important role of COUP-TFI in CXCL12 expression and the importance of the CXCL12 signaling axis in tumor growth and metastasis, the effects produced by glyceollins seem very important." (PMID 28666461, 2017). "CXCR4 expression has also been linked to over 20 different types of cancer like breast cancer, colon cancer, prostate cancer and melanoma demonstrating that the CXCR4/CXCL12-axis is involved in tumor progression, angiogenesis, metastasis and survival." (PMID 28356064, 2017). "In contrast, CXCL8/IL-8 which is over expressed in tumours of the Take group and CXCL12/SDF-1alpha are found in some mesenchymal regulons and have been shown to cooperatively promote invasiveness and angiogenesis in pancreatic cancer." (PMID 28588211, 2017). "Further evidences suggest a critical role of the CXCL12/CXCR4 axis in tumor initiation, metastatic colonization and resistance to chemotherapy." (PMID 28176874, 2017). "Tumour cells moved towards the highest concentration CXCL12 gradients, realizing the directional migration and positive feedback mechanisms in an autocrine manner." (PMID 28403883, 2017). "In this work, we study CXCL12 gradients in tumor geometries that are likely to exist in vivo while simultaneously examining the role of endothelial CXCR7." (PMID 29117251, 2017). "Like IgG4 formats, IgG1 antibodies are antagonist that block tumor cell chemotaxis toward CXCL12 and induce tumor cell apoptosis in either presence or absence of stromal cells." (PMID 29387053, 2017). "In glioblastoma, a portion of the tumor vasculature arises from CSCs which have been reported to differentiate to tumor vessel pericytes upon CXCL12/CXCR4 and TGFβ signaling." (PMID 29112161, 2017). "In the present study, we identified a significant increase in CXCL4, CXCL12, and Cyclin D1 expression in tumor samples from Chinese patients with sporadic MPNST." (PMID 29020982, 2017). "In these cases, a dominant source of chemokine is CXCL12 originating from distant sites in the body that is delivered to the tumor via the blood circulation." (PMID 29117251, 2017). "Senescent cells in tumour emboli of lymphovascular channels and in metastatic lymph nodes expressed CXCL12." (PMID 28489070, 2017). "The CXCR4/CXCL12 axis is used by tumor cells which secrete platelet-derived growth factor (PDGF) that in turn activates endothelial cells to secrete CXCL12 leading to a chemotaxis gradient." (PMID 28785589, 2017).
tumor (continued). "We showed that epigenetic modifications, including defects in promoter histone acetylation in MSS carcinomas and DNA methylation in MSI samples, decreased CXCL12 expression in tumor tissue." (PMID 28418886, 2017). "As it is known to all, CXCL12/CXCR4 plays an important role in maintaining tumor invasion and metastasis." (PMID 28193907, 2017). "The chemokine CXCL12 and its receptor CXCR4 has been demonstrated to cause tumor progression and metastasis." (PMID 28658303, 2017). "Tissue decolorization and 3D reconstitution successfully emphasized remarkable expansion of Cxcl12/Cxcr4 expressing cells within antral tumor." (PMID 29340033, 2017). "In this study, we addressed this question by measuring the expression of CXCR4, CXCL12, and Cyclin D1 proteins in tumor samples from Chinese patients with sporadic MPNST." (PMID 29020982, 2017). "While Cxcr4+ epithelial cells are normally at the gland base surrounded by Cxcl12+ endothelial cells, there was marked expansion of Cxcr4+ epithelial cells to within the antral tumor." (PMID 29340033, 2017). "The chemoattractant CXCL12 (aka., SDF-1), produced by GBM-tumor-associated microglia/macrophages and endothelial cells, also promotes GBM invasion through interactions with CXCR4." (PMID 28883992, 2017). "Their product NOX-A12 functions as a CXCL12 inhibitor and enabled the release of CXCL12 from the surface of tumor stromal cells and blocked its interaction with cell surface receptors CXCR4 and CXCR7." (PMID 28620386, 2017). "Stroma-derived cytokine CXCL12 is taken up by tumor cells and promotes tumor progression, metastasis and chemoresistance." (PMID 28383487, 2017). "As CXCL12 is secreted in the tumor environment, it diffuses away, binds to extracellular matrix (ECM), and is degraded by both cellular and extracellular means." (PMID 29117251, 2017). "CXCR4 and ACKR3 as well as CXCL12 are frequently overexpressed in human cancers where they contribute to tumor growth and metastasis formation." (PMID 29156704, 2017). "The original view of stromal cell-secreted CXCL12 acting on CXCR4-expressing tumor cells in a paracrine manner has evolved in recent years." (PMID 28055968, 2017). "The data showed that CXCL12 treatment or CXCL12 treatment combined with CXCR4 overexpression reduced the anti-tumor effect of SGC-7901 and MKN-45 gastric cells to regorafenib." (PMID 28489887, 2017). "Targeting tumor-specific growth promoting pathways is important for successful cancer therapy, and the CXCL12/CXCR4 signaling axis is involved in tumor progression and migration in multiple tumor types." (PMID 28055968, 2017). "Firstly, side effects of CXCL12/CXCR4 axis inhibitors upon extra‐tumor tissues or cells exist objectively, although some inhibitors have been clinically approved." (PMID 28544785, 2017). "Before moving on to tumor microenvironment simulations, we wanted to understand the interdependence of circadian fluctuations in CXCL12 concentrations and endothelial CXCR7 cells." (PMID 29117251, 2017). "The atypical chemokine receptor 3 (ACKR3), which does not couple to G-proteins and does not mediate cell migration, acts as a scavenger for CXCL11 and CXCL12, interfering with the tumor homing CXCL12/CXCR4 axis." (PMID 29156704, 2017). "Deletion of Cxcl12 in endothelial cells or pharmacological blockade of Cxcr4 inhibits antral tumor growth." (PMID 29340033, 2017). "Overall, the optical density of CXCL12 mRNA and protein in 50 cases of tissues is 0.85 ± 0.11, and 1.22 ± 0.16, respectively, compared with those in paired non-tumor tissues (0.29 ± 0.06, and 0.35 ± 0.06, respectively)." (PMID 29254162, 2017). "Here, we report a new mechanism of E5 greatly decreasing tumor microenvironment angiogenesis by inhibiting the CXCL12-induced recruitment of endothelial progenitor cells in addition to its inhibitory effects on tumor cells." (PMID 29263923, 2017).
tumor (continued). "Taken together, these data imply that cell-derived CXCL12-β and -γ within tumor tissue form stronger gradients and create environments richer in CXCL12 than cell-derived CXCL12-α." (PMID 29117251, 2017). "The results of this study provide motivation that CXCL12 isoforms, the cellular composition of a tumor, and circadian rhythm fluctuations dynamically influence CXCL12 gradients." (PMID 29117251, 2017). "Here, we use a computational model to understand the generation of CXCL12 gradients and calculate both the magnitude and direction of those gradients in a tumor microenvironment over time." (PMID 29117251, 2017). "The diagnostic accuracy of CXCR4 was similar to CRP, much higher than that for CXCL12 and classical tumor markers and increased to 77% in combination with CRP." (PMID 27041792, 2016). "In this context the important role of the CXCL12-CXCR4 axis is further supported by recent studies which show upregulated expression of CXCR4 and CXCL12 after chemotherapy, thus leading to invasive and metastatic tumor progression." (PMID 27835905, 2016). "This trip requires the cancer cell to be able to leave the primary tumor, migrate and degrade or re-model the extracellular matrix while invading through the stroma and the availability of the local gradient of CXCL12 and vascular vessels." (PMID 26993780, 2016). "Abrogation of CXCL12 enhanced tumor response to immune checkpoint therapy, potentially explaining the known resistance of PDAC to therapies such as pembrolizumab (a PD‐1 antagonist)." (PMID 26747091, 2016). "Previous studies have shown that CXCL14 interferes with IL-8 and CXCL12 signaling, which are important for tumor cell migration and invasion." (PMID 27143385, 2016). "In this way, it is proposed that CAFs can add selection pressure to heterogeneous tumour cell populations, priming them for bone metastasis through exposure to CXCL12 and IGF1." (PMID 27782035, 2016). "We added AMD3100 to block the interaction of CXCL12 with CXCR4 during the LDH release assay while testing B cell cytotoxicity against 4T1 tumor cells." (PMID 27528023, 2016). "HIF-1 consequently induces tumor secretion of CXCL12, which binds to CXCR4 on proangiogenic bone marrow–derived cells (BMDCs), recruiting them to become endothelial cells within the tumor." (PMID 27863376, 2016). "In this present study, we examined new mechanisms contributing to direct B cell-mediated antitumor immunity, including the impact of IL-2, the CXCR4/CXCL12 pathway and perforin in mediating tumor regression after the adoptive transfer of B effector cells." (PMID 27528023, 2016). "The expression of Cxcl12 and Ccl2 was also measured in the tumor microenvironment, and data show the expression of Cxcl12 and Ccl2 to be increased in the HSC co-transplantation group." (PMID 26758420, 2016). "Our data indicate that A2BR stimulation can enhance the expression of CXCL12, which contributes to its pro-tumor activity." (PMID 27590504, 2016). "TGFβ has also been documented to upregulate CXCL12 in human gingival fibroblasts, tumor-promoting mammary stromal fibroblasts and rat kidney fibroblasts." (PMID 27434301, 2016). "Exposure to chemoattractant triggered tumor cell migration towards a CXCL12 gradient in a concentration dependent manner." (PMID 27835905, 2016). "The diagnostic accuracy of CXCR4 (71%) was similar to CRP (72%), much higher in comparison to CXCL12 (59%) and classical tumor markers (CEA: 49%, SCC-Ag: 46%), and increased to 77% in combined measurement with CRP." (PMID 27041792, 2016). "CXCL12 can also control tumor cell apoptosis, activating NF-κB, which represses radiation-induced tumor necrosis factor α (TNFα) production and tumor apoptosis." (PMID 26880981, 2016). "Namely, CXCL12 expression in CRC cells appears to be bidirectional: tumor promotive or tumor suppressive." (PMID 27136535, 2016).
tumor (continued). "The CXCL12/CXCR4 axis promotes tumor angiogenesis through multiple mechanisms that lead to the recruitment of CXCR4 positive vascular cells into tumor lesions and/or up-regulation of pro-angiogenic factors such as VEGF or other mediators [reviewed in Ref 30]." (PMID 27590504, 2016). "Because the GPCR CXCR7 also binds to CXCL12 and has been shown to have a potential a role in tumor growth and metastasis, we also compared CXCR7:GRK3 expression ratios, but they did not correlate with invasive phenotype." (PMID 27049755, 2016). "AMD3100, a small molecule antagonist of CXCR4, has been reported to inhibit CXCL12-induced tumor metastasis." (PMID 27191997, 2016). "The CXCL12/CXCR4 axis forms critical communication bridges between tumor cells and stromal cells to create a permissive microenvironment for tumor growth and metastasis." (PMID 27293448, 2016). "The histological observations about expression of CXCL12 in pancreatic intraepithelial neoplasia and PC as well as its prognostic significance in PC support its role as a tumor promoter." (PMID 27542220, 2016). "Recent data suggest a chief position of the CXCR4/CXCL12 axis initializing androgen dependent proliferation, tumor cell motility, and metastatic growth in PCa." (PMID 27462860, 2016). "The same mechanisms, which maintained HSC quiescence, are also implicated in tumour cell dormancy (CXCR4, CXCL12 and angiopoietin-1)." (PMID 27782035, 2016). "Recent studies have shown that several proinflammatory chemokines such as IL-8, CXCL1, and CXCL12 drive cancer progression by facilitating tumor cell growth, survival, and migration as well as by inducing angiogenesis." (PMID 27143385, 2016). "Blockade of FasL and CXCR4 concurrently inhibited B cell-mediated direct killing of tumor cells in an additive manner, indicating that both Fas/FasL and CXCL12/CXCR4 pathways are involved in the direct killing of 4T1 cells by 4T1 TDLN B cells." (PMID 27528023, 2016). "The percentages of elevated results (diagnostic sensitivity) of CXCR4 (80%) were higher than those of CXCL12 (47%) and much higher than classical tumor markers—CEA (22%) and SCC-Ag (14%) as well as CRP (57%)." (PMID 27041792, 2016). "Emerging evidence indicates that chemokine receptors pathways control tumor development, including tumor growth, progression, and metastasis and that CXCL12/CXCR4 activation induces migration and metastatic processes." (PMID 26934559, 2016). "This was recapitulated by blocking the activity of CAF‐secreted cytokine CXCL12, preventing activity on tumor cells to effectively exclude anti‐tumor T cells." (PMID 26747091, 2016). "An additional chemokine/receptor axis involved in migration of neutrophils into tumor site is CXCL12/CXCR4 axis." (PMID 28066438, 2016). "It has been reported that increased expression of CXCL12 is a strong positive prognostic factor that correlates with disease free and overall survival in both ER+ and ER- tumours." (PMID 27469239, 2016). "CXCL12 (SDF-1) can also be expressed by tumor cells and it results in increased macrophage and microvessel density and in vivo invasiveness." (PMID 27901093, 2016). "The CXCR4/CXCL12 axis represents a major mechanism in tumor growth and metastasis, and its role in the cancer cell-tumor microenvironment has recently been studied regarding cancer progression and the attraction/activation of leukocytes." (PMID 27528023, 2016). "The chemokine CXCL12/stromal cell-derived factor-1 is important for leukocyte migration to lymphoid organs and inflamed tissues and stimulates tumor development." (PMID 27566567, 2016). "Our data support the postulate, that CXCL12 methylation down-regulates tumor intrinsic CXCL12 protein expression in PCa as well, thereby fostering metastasis." (PMID 27462860, 2016). "The CXCL12-dependent signalling has emerged among the most relevant molecular pathways that can be targeted to successfully interfere with tumor cell proliferation, survival, migration, and radioresistance." (PMID 27015814, 2016).
tumor (continued). "Ccl5 and Cxcl12 were strongly expressed in the brains of mice that developed tumours after ESC or iPSC transplantation; the expression levels of these genes were also positively correlated with the malignant grades of the tumours." (PMID 27417157, 2016). "CXCR4-expressing tumor cells preferentially colonize distant organs that secrete high levels of CXCL12, such as brain, lungs, lymph nodes, liver and bone marrow." (PMID 26744352, 2016). "The ligand for CXCR4, namely, CXCL12, is secreted by ECs and the immune cells in tumor microenvironment, which highlights the importance of CXCL12/CXCR4 axis in the maintenance of GSCs in vascular niches." (PMID 26977157, 2016). "Binding to CXCL-12 can block its receptor binding and prevent CXCL-12 tissue gradients and decrease the possibility of tumor metastasis and drug resistance caused by cancer cell homing." (PMID 26978355, 2016). "Endogenous type I IFNs inhibit CXCR4 expression on neutrophils and block CXCL12 expression in tumors leading to suppressed migration of neutrophils toward the tumor." (PMID 28066438, 2016). "Of note, blockade of FasL and CXCR4 simultaneously inhibited B cell-mediated killing of tumor cells in an additive manner, indicating that both Fas/FasL and CXCR4/CXCL12 axes are involved in the killing of tumor cells by B cells." (PMID 27528023, 2016). "Among them, lymphatic endothelial cells secrete chemokines such as CXCL12 that can promote tumor cells expressing the cognate receptor CXCR4 to migrate toward the lymphatic vessels, promoting a lymphatic microenvironment that supports tumor growth." (PMID 27806339, 2016). "Increased levels of CXCL12 in blood plasma correlated with the recruitment of circulating endothelial progenitor cells to the tumor promoting vascularization and repopulation of resistant tumor cells." (PMID 27835905, 2016). "Five of these genes, CXCL12, MMP2, MMP11, VCAM1, and MME, which have previously been associated with tumor progression, angiogenesis, and metastasis, clearly discriminated between primary BC and BCBM." (PMID 27340107, 2016). "Further studies are necessary to investigate the influence of CXCL12 on tumor cell mortality in the context of ESCC." (PMID 27439769, 2016). "Here, we show that the cross communication between human tumor cells and zebrafish ligands is maintained, because zebrafish Cxcl12 activates human CXCR4 signaling in vitro and supports the formation of TNBC early metastases in vivo." (PMID 26744352, 2016). "For instance, the pro-inflammatory cytokine CXCL12 produced by CAFs stimulate the proliferation and migration of tumor cells interacting with the cognate receptors expressed by cancer cells." (PMID 27072893, 2016). "NOX-A12 targets to stroma cell-derived factor-1 The chemokine (C–X–C motif) ligand 12 (CXCL-12), which plays important roles in stem cell migration towards the bone marrow and controls tumor growth, metastasis and vasculogenesis." (PMID 26978355, 2016). "Microenvironment conditions such as hypoxia induce CXCR4 expression which further sensitizes tumor cells to signals such as CXCL12 and promotes tumor metastasis." (PMID 26884752, 2016). "High CXCL12 concentration at a target organ induces integrin activation and subsequent migration of tumor cells across the endothelium, thus leading to organ-specific metastasis formation." (PMID 27835905, 2016). "Gene methylation adds to the major regulatory alterations interfering with CXCL12 homeostasis in tumor epithelium, leading to a silenced CXCL12 signal in various human malignant tumors." (PMID 27462860, 2016). "Autocrine tumor growth factor beta (TGF-β) and CXCL12 signaling loops initiate and maintain the differentiation of fibroblasts into myofibroblasts and the concurrent tumor-promoting phenotype." (PMID 27136535, 2016). "CXCR4 showed a nuclear positivity in all samples, but only CXCL12 expression in tumor endothelial cells was significantly correlated with shorter survival." (PMID 27018053, 2016).